POLR1A (RNA polymerase I subunit A)
Description:
Catalytic core component of RNA polymerase I (Pol I), a DNA-dependent RNA polymerase which synthesizes ribosomal RNA precursors using the four ribonucleoside triphosphates as substrates. Transcribes 47S pre-rRNAs from multicopy rRNA gene clusters, giving rise to 5.8S, 18S and 28S ribosomal RNAs. Pol I-mediated transcription cycle proceeds through transcription initiation, transcription elongation and transcription termination stages. During transcription initiation, Pol I pre-initiation complex (PIC) is recruited by the selectivity factor 1 (SL1/TIF-IB) complex bound to the core promoter that precedes an rDNA repeat unit. The PIC assembly bends the promoter favoring the formation of the transcription bubble and promoter escape. Once the polymerase has escaped from the promoter it enters the elongation phase during which RNA is actively polymerized, based on complementarity with the template DNA strand. Highly processive, assembles in structures referred to as 'Miller trees' where many elongating Pol I complexes queue and transcribe the same rDNA coding regions. At terminator sequences downstream of the rDNA gene, PTRF interacts with Pol I and halts Pol I transcription leading to the release of the RNA transcript and polymerase from the DNA. Forms Pol I active center together with the second largest subunit POLR1B/RPA2. Appends one nucleotide at a time to the 3' end of the nascent RNA, with POLR1A/RPA1 contributing a Mg(2+)-coordinating DxDGD motif, and POLR1B/RPA2 participating in the coordination of a second Mg(2+) ion and providing lysine residues believed to facilitate Watson-Crick base pairing between the incoming nucleotide and the template base. Typically, Mg(2+) ions direct a 5' nucleoside triphosphate to form a phosphodiester bond with the 3' hydroxyl of the preceding nucleotide of the nascent RNA, with the elimination of pyrophosphate. Has proofreading activity: Pauses and backtracks to allow the cleavage of a missincorporated nucleotide via POLR1H/RPA12. High Pol I processivity is associated with decreased transcription fidelity (By similarity).
Synonyms: RPA194; DKFZP586M0122; FLJ21915; RPO1-4; RPA1; RPA190; A190; AFDCIN; HLD27; RPO14
Tractability: Small molecule: a drug acting on it is in phase 2 or 3 trials; a structure with a bound ligand is known; a high-quality ligand is known. PROTAC: ubiquitination databases record sites on it; its protein half-life has been measured; a small molecule that binds it is known.
Target class: Enzyme; Transferase
Gene: Protein-coding gene on chromosome 2 (86,020,216 to 86,106,155, reverse strand). Ensembl gene ENSG00000068654.
Subcellular location: Nucleus, nucleolus; Chromosome
Subcellular location (Human Protein Atlas): Nucleoli fibrillar center; Cytosol; Nucleoplasm
Pathways (Reactome):
Gene expression (Transcription): B-WICH complex positively regulates rRNA expression; NoRC negatively regulates rRNA expression; RNA Polymerase I Promoter Escape; RNA Polymerase I Transcription Initiation; RNA Polymerase I Transcription Termination
Gene Ontology:
Molecular function: 5'-3' RNA polymerase activity; chromatin binding; DNA-directed RNA polymerase activity; DNA/RNA hybrid binding; magnesium ion binding; protein binding; zinc ion binding; DNA binding
Biological process: negative regulation of protein localization to nucleolus; transcription by RNA polymerase I; transcription elongation by RNA polymerase I; nucleolar large rRNA transcription by RNA polymerase I; termination of RNA polymerase I transcription; transcription initiation at RNA polymerase I promoter; DNA-templated transcription
Cellular component: chromatin; fibrillar center; RNA polymerase I complex; chromosome; nucleoplasm; nucleus; nucleolus
Genetic constraint (gnomAD): Loss-of-function variants: 72 observed, 182.95 expected, observed/expected ratio (o/e) 0.39, 90% interval 0.32 to 0.48. The upper end of that interval is the gene's LOEUF score, 0.48, which puts it in group 2 of 6, group 1 being the genes least tolerant of losing a copy. Missense variants: 1,502 observed, 2,132.2 expected, observed/expected ratio (o/e) 0.7, 90% interval 0.67 to 0.74. Synonymous variants: 745 observed, 843.21 expected, observed/expected ratio (o/e) 0.88, 90% interval 0.83 to 0.94.
Homologues: Orthologues: chimpanzee POLR1A (99% identical), macaque POLR1A (98% identical), dog POLR1A (91% identical), rabbit POLR1A (91% identical), pig POLR1A (90% identical), guinea pig POLR1A (88% identical), rat Polr1a (88% identical), mouse Polr1a (87% identical), tropical clawed frog polr1a (70% identical), zebrafish polr1a (67% identical), Drosophila melanogaster Polr1A (42% identical), Caenorhabditis elegans rpoa-1 (39% identical). Paralogues in human: POLR2A (24% identical), POLR3A (24% identical).
Diseases named in the same sentence as POLR1A in open-access papers:
POLR1A is named in the same sentence as 24 diseases in open-access papers, as found by Europe PMC text mining. Sharing a sentence is not in itself a finding about the gene and the disease. The quoted sentences say what the papers report.
acrofacial dysostosis (4 papers, 2016 to 2025). "Patients with POLR1A gene-related variants present with Acrofacial Dysostosis, Cincinnati-type, and recently shown to be associated with neural and cardiac abnormalities." (PMID 41010008, 2025). "Consistent with this idea, we recently identified mutations in the RNA Pol I subunit, POLR1A, in association with another ribosomopathy disorder, Acrofacial dysostosis, Cincinnati type." (PMID 27448281, 2016). "Disorders caused by POLR1A and related gene variants, including Acrofacial Dysostosis—Cincinnati type, Treacher–Collins syndrome types 2–4, and TWIST1-associated syndromes such as Saethre–Chotzen and Sweeney–Cox, exhibit overlapping craniofacial and developmental phenotypes." (PMID 41010008, 2025). "Pathogenic heterozygous variants in POLR1A are associated with acrofacial dysostosis, Cincinnati type, the symptoms of which include large and low-set ears, downslanting palpebral fissures, an underdeveloped midface, micrognathia, decreased head circumference and short stature." (PMID 38137045, 2023). "His findings were clinically and genetically consistent with Acrofacial Dysostosis, Cincinnati-type, supported by a POLR1A gene defect." (PMID 41010008, 2025).
breast carcinoma (4 papers, 2019 to 2025). "Analysis of TCGA breast cancer patient data confirms a reliance of breast tumors on RNA Pol I activity as determined by a significant correlation of high POLR1A expressing tumors with decreased overall survival." (PMID 37380890, 2023). "Recently, Gold-NPs have been shown to disrupt the nucleolar integrity in breast cancer cell lines by affecting the nucleolar/nucleoplasmatic distribution of several proteins such as the NPM1, the RNA Polymerase I Subunit A (RPA194), the Heat Shock Protein hsp70 and O-GlcNAc-modified proteins." (PMID 31527430, 2019). "Additionally, we observed downregulation of genes such as POLR1A, POLR1D, POLR1E, TAF1B, LAMP1, and CDKN1A in response to AQ treatment demonstrating the role of AQ in regulating RNA polymerase subunits and effect on overall gene transcription in breast cancer." (PMID 36232751, 2022).
melanoma (3 papers, 2019 to 2026). A malignant, usually aggressive tumor composed of atypical, neoplastic melanocytes. "Here, we employed in vivo CRISPR knockout screening targeting the genes associated with poor prognosis to identify Polr1a as a potent driver of melanoma metastasis." (PMID 42310097, 2026). "Polr1a inhibition suppressed migration, invasion, and the ability of melanoma cells to colonize lungs." (PMID 42310097, 2026). "Indeed, targeting Polr1a decreased levels of RelB and p52 and suppressed non-canonical NF-κB transcriptional activity; this suppression was responsible for the effects of Polr1a on melanoma cell migration." (PMID 42310097, 2026).
leukodystrophy (2 papers, 2023 to 2024). Leukodystrophies are a group of rare, progressive, metabolic, genetic diseases that affect the brain, spinal cord and often the peripheral nerves. "We previously reported a homozygous variant in the catalytic subunit of RNA polymerase I, POLR1A, in two brothers with leukodystrophy and progressive course." (PMID 36917474, 2023). "In conclusion, we confirm that biallelic pathogenic POLR1A variants cause leukodystrophy with recessive inheritance, and provide for the first-time preliminary insight into possible cellular consequences of POLR1A dysfunction." (PMID 36917474, 2023). "Ostensibly autosomal recessive hypomyelinating leukodystrophy (HLD) has been linked to autosomal recessive mutations in POLR1A (HLD27) and POLR1C (HLD11)." (PMID 38791054, 2024). "Experiments in patient fibroblasts reveal aberrant rRNA processing, nucleolar stress, and impaired protein homeostasis, providing new information about the molecular basis of POLR1A-related leukodystrophy." (PMID 36917474, 2023). "We confirm that POLR1A biallelic variants cause neurodegenerative disease, expand the knowledge of the clinical phenotype of the disorder, and provide evidence for possible pathological mechanisms leading to POLR1A-related leukodystrophy." (PMID 36917474, 2023). "The suggested pathological mechanism in POLR1A-related leukodystrophy warrants further validation." (PMID 36917474, 2023).
acrofacial dysostosis Cincinnati type (1 paper, 2023). Any acrofacial dysostosis in which the cause of the disease is a mutation in the POLR1A gene. "More specifically, mutations in POLR1A cause Acrofacial Dysostosis Cincinnati type (AFDCin), whereas mutations in POLR1B, POLR1C and POLR1D and the Pol I associated protein, TCOF1/TREACLE lead to Treacher Collins Syndrome (TCS)." (PMID 37639467, 2023).
Atrophy (1 paper, 2025). Any weakening or degeneration, especially through lack of use. "While there is currently no direct evidence linking Polr1a or NCL to cortical development, these prior findings suggest that their loss could plausibly contribute to cortical atrophy." (PMID 40676207, 2025).
colon adenocarcinoma (1 paper, 2022). "The expression levels of POLR1A and CMYC, measured by log2 median-centered ratios, were significantly higher in colon adenocarcinoma than that in the non-tumoral tissues." (PMID 35681628, 2022).
colorectal cancer (1 paper, 2024). A primary or metastatic malignant neoplasm that affects the colon or rectum. "Inhibition of POLR1A was found to regulate the signaling pathways and cell functions in colorectal cancer, so its trans-regulating TFs may also be involved." (PMID 38632500, 2024).
colorectal tumors (1 paper, 2022). "As expected, ΔCt POLR1A and ΔCt CMYC decreased in CRC, meaning that both POLR1A and CMYC were overexpressed in colorectal tumors compared with non-tumoral tissues." (PMID 35681628, 2022).
glioma (1 paper, 2019). A benign or malignant brain and spinal cord tumor that arises from glial cells (astrocytes, oligodendrocytes, ependymal cells). "This will enhance the translation of a number of key genes associated with malignant progression of gliomas, such as c-Myc, NRF2, TERT, POLR1A, and POLR2A." (PMID 30936423, 2019).
cancer (15 papers, 2014 to 2024). A tumor composed of atypical neoplastic, often pleomorphic cells that invade other tissues. "Cancer cells with active protein translation are characterized by elevated levels of RNA Polymerase I subunit A (POLR1A), one of the key components of RNAPOL1." (PMID 35673898, 2022). "Pol I activity and POLR1A abundance have also been considered as promising biomarkers for the identification of cancers sensitive to Pol I inhibition, leading to the development of an rRNA transcription assay applicable to human cancer specimens." (PMID 35565259, 2022). "BMH-21 induces degradation of POLR1A in several cancer cell lines including U2OS, but this degradation is not universal, and therefore is not observed in some cancer and normal-like cell lines, including BJ fibroblasts." (PMID 38340348, 2024).
tumor (7 papers, 2020 to 2026). "TAF1A (TATA-box binding protein associated factor, RNA polymerase I subunit A) was also a highly up-regulated gene in both cell lines, although it was significantly down-regulated in the tumor (x(T) = −2.12; x(Φ) = 105.70; x(Θ) = 128.88)." (PMID 38790250, 2024). "Accordingly, pharmacological inhibition of Polr1/Polr1a suppressed cell migration, tumor growth, and metastases." (PMID 42310097, 2026). "We observed a zonation of POLR1A from higher levels at the border to lower levels in the tumor center." (PMID 35673898, 2022). "CRC stem cells with high expression of PolR1A were classified at the top of tumor stem cell hierarchy and ip injection of BMH-21 induced a significant decrease in PolR1A-high stem cell and in tumor xenograft growth." (PMID 33120992, 2020). "In addition, depletion of POLR1A in LGR5 high cells prevents tumor formation." (PMID 35673898, 2022). "Besides, PolR1A is shown as one of the prerequisites for in vivo tumor growth." (PMID 33120992, 2020). "To gain a better understanding and to expand upon this observation, we irradiated tumor cells and stained for GLI1, POLR1A, and TCOF1." (PMID 37380890, 2023). "Furthermore, high levels of POLR1A define a stemness compartment independent of LGR5 expression and drive in vivo tumor formation of LGR5 low cells." (PMID 35673898, 2022).
neurodegenerative disease (1 paper, 2023). A disorder of the central nervous system characterized by gradual and progressive loss of neural tissue and neurologic function. "In conclusion, our results confirm that biallelic POLR1A variants cause a neurodegenerative disease." (PMID 36917474, 2023).
POLR1A also shares sentences with these, for which no sentence is quoted: colon cancer (2 papers); mandibulofacial dysostosis (2); Autoimmunity (1); breast tumors (1); hepatocellular carcinoma (1); infection (1); neurological diseases (1); pancreatic cancer (1); scleroderma (1); Treacher-Collins syndrome (1); viral infections (1).